NAV3 (neuron navigator 3)
Diseases named in the same sentence as NAV3 in open-access papers (continued):
Sharing a sentence is not in itself a finding about the gene and the disease.
endometrial carcinoma (2 papers, 2019 to 2025). A malignant tumor arising from the epithelium that lines the cavity of the uterine body. "Our large study extends the number of genome-wide significant risk loci identified for endometrial carcinoma by about one-third and proposes a role of NAV3 as a tumour suppressor in this common cancer." (PMID 40633141, 2025). "High protein expression in a non-malignant endometrial cell line and the markedly reduced expression in all tested endometrial cancer lines further indicated a potential role of NAV3 as a tumour suppressor in the endometrium and was consistent with TCGA expression data." (PMID 40633141, 2025). "To further establish the role of NAV3 in endometrial cancer, we overexpressed EGFP-fused wildtype (EGFPN1-NAV3WT) and mutant (EGFPN1-NAV3D1047N) NAV3 in Ishikawa cells, with the latter being used as functionally inactive negative control." (PMID 40633141, 2025). "Our endometrial carcinoma analysis offered especially interesting results as it returned numerous pairs of networks with similarity, where most of the corresponding genes in these pairs - such as CTCF, NAV3, and ZFHX3 - are not typically implicated as markers of drug response." (PMID 31253832, 2019).
Human papillomavirus infection (2 papers, 2022 to 2023). "SRRM4 is a known regulator of alternative splicing, while NAV3 is reported to be involved in multiple immune and infection-associated pathways such as FoxO signaling, T cell activation, and Human papillomavirus infection pathways." (PMID 37604131, 2023).
leukemia (2 papers, 2014 to 2022). A malignant (clonal) hematologic disorder, involving hematopoietic stem cells and characterized by the presence of primitive or atypical myeloid or lymphoid cells in the bone marrow and the blood. "The identification of ∼600 bp of a RAS related leukemia viral oncogene (LOC642550) proximal to the L1 retrotransposon within the NAV3 -SYT1-PAWR gene cluster is also of interest given the known and shared role of rearrangement mediated FUS gene fusions between myxoid liposarcoma and leukemia." (PMID 24505276, 2014).
microcephaly (2 papers, 2024 to 2025). A congenital or acquired developmental disorder in which the circumference of the head is smaller than normal for the person's age and sex. "In family 2, the patient harboring a homozygous NAV3 variant (c.243 + 1G > T) presents with the most notable clinical manifestations of microcephaly and learning disabilities." (PMID 39708122, 2025). "Although our sample is not large enough for a meaningful genotype-phenotype correlation, intriguingly, individuals with biallelic NAV3 variants had severe ID with the prevalence of other features such as microcephaly, skeletal deformities, and behavioral problems." (PMID 38977784, 2024). "The nav3 morphants (nav3-MO) were found to have severe behavioral and morphological defects, including microcephaly and impaired neuronal growth." (PMID 39708122, 2025). "Further, knocking-down nav3 in zebrafish led to severe morphological defects, microcephaly, impaired neuronal growth, and behavioral impairment, which were rescued with co-injection of WT NAV3 mRNA and not by transcripts encoding the pathogenic variants." (PMID 38977784, 2024).
migraine (2 papers, 2019 to 2022). "The in-silico analysis showed that the target genes, i.e., HCN3, NAV3, GPR158 for miR-34a-5p and MTPN for miR-375, are involved in trigeminal pain circuit of migraine." (PMID 35682695, 2022). "In particular, HCN3 belong to hyperpolarization-activated potassium channels family proteins involved in trigeminal ganglion neuron activation, while NAV3 and GPR158 are emerging in migraine." (PMID 31252698, 2019).
adenoma (1 paper, 2012). A neoplasm arising from the epithelium. "We analysed changes in chromosome 12 and NAV3 copy number in CRC/adenoma samples of 59 patients and in 6 CRC cell lines, using fluorescence in situ hybridisation, loss of heterozygosity, and array-CGH." (PMID 22173670, 2012). "NAV3 copy number changes and elevated IL-23R expression (moderate or strong immunostaining), and/or nuclear beta-catenin were present in three of the adenoma samples." (PMID 22173670, 2012). "For 11 MSS-type CRC patients, it was possible to compare the IL-23R, beta-catenin, and NAV3 FISH results in matched adenoma and tumour samples." (PMID 22173670, 2012). "Comparison of NAV3 copy numbers between adenoma and carcinoma samples from the same intestinal resection samples of a given patient revealed that NAV3 deletion also was frequently detectable at the adenoma stage, however at lower frequency than in the corresponding carcinoma sample." (PMID 22173670, 2012). "NAV3 copy number changes are frequent in CRC and in adenomas, and upregulation of IL23R, following NAV3 silencing, strongly correlates with Dukes’ staging and lymph node metastases." (PMID 22173670, 2012). "Cells with NAV3 deletion were also detected in 12.5% of MSI-type samples and 23% of adenoma samples." (PMID 22173670, 2012). "NAV3 deletion and chromosome 12 polysomy were detected in 30 and 70% of microsatellite stability (MSS) carcinomas, in 23 and 30% of adenomas and in four of six CRC cell lines." (PMID 22173670, 2012). "Because of the small number of adenoma samples in these surgical resections, it was not possible to assess correlation between the NAV3 copy number changes, IL-23R and beta-catenin expression, biological behaviour, and prognostic features of the disease." (PMID 22173670, 2012).
cardiac hypertrophy (1 paper, 2022). "We found that lncRNA Airn, lncRNA Ttc4, lncRNA Ablim1 and lncRNA Nav3 were novel lncRNAs associated with cardiac hypertrophy." (PMID 35402096, 2022).
cervical cancer (1 paper, 2022). A primary or metastatic malignant neoplasm involving the cervix. "In addition, our study firstly revealed the somatic mutations of KMT2D, NAV3 and PKHD1L1 in cervical cancer, to our knowledge." (PMID 36076209, 2022).
colon adenoma (1 paper, 2012). An adenoma that arises from the colon. "We now report that NAV3 copy number changes are found frequently in MSS type CRC, colon adenomas, and established CRC cell lines." (PMID 22173670, 2012).
colorectal adenoma (1 paper, 2015). An adenoma that arises from the colon or rectum. "Deletion of NAV3 was detected in colorectal adenomas, cancer tissue and cell lines, the NAV3 aberrations provided two growth advantages to a subpopulation of microsatellite stability CRC linked to inflammation and cell proliferation pathways." (PMID 26452645, 2015).
COVID-19 (1 paper, 2023). A disease caused by infection with severe acute respiratory syndrome coronavirus 2. "Most recently, both SRRM4 and NAV3 were reported to be upregulated in the COVID-19 patients’ nasopharyngeal tissue, indicating yet to be discovered specific functional roles, especially during infectious diseases, and awaits investigating the functional role in a focused way." (PMID 37604131, 2023). "Notably, we observed an overall higher association of protein coding transcripts, especially NAV3 and SRRM4, with the metabolic process and cytoskeleton organization associated pathways, suggesting a significant role of protein coding transcript isoforms in the COVID-19 pathogenesis." (PMID 37604131, 2023).
endometrial tumours (1 paper, 2025). "Functional genomic data from endometrial tumours and cell lines revealed NAV3 as a candidate regulatory target of risk variation at this risk locus." (PMID 40633141, 2025).
epilepsy (1 paper, 2021). A brain disorder characterized by episodes of abnormally increased neuronal discharge resulting in transient episodes of sensory or motor neurological dysfunction, or psychic dysfunction. "These isoforms are conserved in rodents and humans, which highlights the relevance of Nav3 circular transcripts in epilepsy and could be further explored." (PMID 33584828, 2021).
Epstein-Barr virus infection (1 paper, 2023). An infection that is caused by Epstein-Barr virus. "NAV3 was involved in adaptive immune response, cytokine-mediated signaling pathway (GO) and epstein-barr virus infection, herpes simplex virus 1 infection (KEGG)." (PMID 36862916, 2023).
hepatocellular carcinoma (1 paper, 2021). A malignant tumor that arises from hepatocytes. "Previous studies identified miR-21-3p target genes: in ovarian cells it targets NAV3, a known tumor suppressor; in hepatocellular carcinoma, it targets SMAD7, an inhibitor of the TGFβ pathway; and in ESCC, it targets TRAF4." (PMID 34797887, 2021).
liposarcoma (1 paper, 2021). A usually painless malignant tumor that arises from adipose tissue. "Many genetic mutations have been reported in dedifferentiated liposarcomas, including mutations in MDM2, CDK4, high mobility group AT-hook 2 (HMGA2), fibroblast growth factor receptor substrate 2 (FRS2), and neuron navigator 3 (NAV3), all located in 12q13-15." (PMID 35008848, 2021).
lung adenocarcinoma (1 paper, 2021). A carcinoma that arises from the lung and is characterized by the presence of malignant glandular epithelial cells. "Predictions of neoantigen recognition in lung adenocarcinoma suggest that NAV3 is one of the most commonly mutated genes with predicted neoantigen recognition in this disease as well." (PMID 34298611, 2021).
lymph node metastases (1 paper, 2012). "The NAV3 copy number changes correlated with chromosome 12 polysomy, as well as with the occurrence of lymph node metastases in the patients." (PMID 22173670, 2012). "NAV3 copy number changes correlated significantly with chromosome 12 polysomy and with lymph node metastasis." (PMID 22173670, 2012).
retinal disease (1 paper, 2017). "According the paper, among these DEGs, PTPRG, CSPG5 and NAV3 are at loci associated with retinal disease; MFAP3L, CSPG5 and PAK1IP1 locate in the regions carrying SNP's significantly associated with AMD." (PMID 28924976, 2017).
Stroke (1 paper, 2024). Sudden impairment of blood flow to a part of the brain due to occlusion or rupture of an artery to the brain. "Moreover, the predominant Mg0 subgroup at subacute stages (7d) after stroke expressed greater Nav3 and Dock4, pivotal for axon outgrowth, guidance, and cellular protection against oxidative stress, implying a neuroprotective potential." (PMID 38988493, 2024).
cancer (26 papers, 2012 to 2026). A tumor composed of atypical neoplastic, often pleomorphic cells that invade other tissues. "Further mutations in cancer-related genes included Nav3 (V1129L), Cenpf (D1327E), Muc5ac (A429P), Mpp7 (Q158R), Gas1 (G326R), Maged2 (A473S), Dusp1 (C24R), Ros1 (W1875C), Polr2a (M1102I), Rragd (L385P), and Hoxa9 (insertion of “G” in UTR)." (PMID 32793490, 2020). "The LOH method used in this study, would not by itself have excluded such an interpretation as changes close to the location of the NAV3 gene (for example, the cancer implicated gene E2F7) would also have shown loss of heterogeneity in this assay." (PMID 22173670, 2012). "In genomic landscaping, NAV3 belongs to the ‘hill type’ candidate cancer gene group, which is commonly mutated in human breast and colon cancer." (PMID 22173670, 2012). "In accordance, deletion of NAV3 gene has been linked to poor prognosis in cancer." (PMID 40950124, 2025). "The second zone is supported by a marker located in the NAV3 gene, on chromosome 12, which encodes a navigator neuron associated with some types of cancer and could be a good prognostic gene and therapeutic target." (PMID 36445690, 2022). "NAV3 is primarily implicated as a metastasis suppressor in multiple cancer types." (PMID 34298611, 2021). "Both deletion of NAV3 and point mutations within several structural domains have been reported in various cancers." (PMID 25678558, 2015). "Another question of importance is whether the observed NAV3 aberrations would be causative factors (‘driver alterations’) in cancer formation or spread, or whether they would represent secondary changes." (PMID 22173670, 2012). "Thus despite incomplete evidence for a direct regulatory mechanism, our findings, together with prior evidence, support the hypothesis that risk variation at this locus increases cancer susceptibility by downregulating NAV3 expression." (PMID 40633141, 2025). "We posit that this puzzling NAV3 expression pattern reflects the phenotypic heterogeneity of cancer cells." (PMID 39097525, 2025). "Both gene expression with qRT-PCR and protein analyses indicated strongly reduced NAV3 expression in cancer cells compared with E6E7hTERT cells." (PMID 40633141, 2025). "Nav3 is aberrantly expressed in diverse tumors and has been shown to direct migration and dissemination of cancer cells." (PMID 34106998, 2021). "Taken together, these results provide evidence that p73 is necessary for NAV3 induction in response to genotoxic stress and that NAV3 plays a pivotal role in p73-mediated inhibition of cancer cell invasion, migration, and metastasis." (PMID 32029709, 2020). "The p73 protein is localised mainly in the nuclei of the cancer cells while NAV3 is expressed mostly in the cytoplasm of the cancer cells." (PMID 32029709, 2020). "For cancer related genes, Nav3, Cenpf, Muc5Ac, Mpp7, Gas1, MageD2, Dusp1, Ros, Polr2a, Rragd, Ros1, and Hoxa9 are mutated." (PMID 32793490, 2020). "This conclusion is consistent with the ability of relatively low NAV3 abundance to predict poorer prognosis of cancer patients." (PMID 25678558, 2015). "This suggests that NAV3 has a role in linking tissue inflammation to cancer development in the colon." (PMID 22173670, 2012). "Notably, low NAV3 expression was correlated with poor prognosis in these cancers." (PMID 35812247, 2022). "Here, we identify Navigator-3 (NAV3), a microtubule-binding protein, as a novel transcriptional target of p73, which gets upregulated by DNA damage in a p73-dependent manner and plays a vital role in p73-mediated inhibition of cancer cell invasion, migration, and metastasis." (PMID 32029709, 2020). "Moreover, these genes had relatively high mutation rates in the pan-cancer data (KMT2D, 14.41%; ARID1A, 9.04%; NAV3, 8.52%), which might be overestimated due to the erroneous batch-biased variant calls, although this remains to be validated." (PMID 28399795, 2017).
cancer (continued). "NAV3 is also a target for exosomal miR-21-3p in promoting CDDP resistance, suggesting an important role of EXs in cell–cell communication in the development of drug resistance in a plethora of cancers, including OVCA." (PMID 31700155, 2020). "Notably, NAV3 has been consistently categorized as a candidate driver in all three authoritative databases (NCG candidate, CancerMine, and CCGD), further supporting its potential role in cancer development." (PMID 41511464, 2026). "Genes such as RLIM, FBL17, FGF7, DDX5, NAV3, and NFASC were found at the intersection of multiple pathways, suggesting they may function as critical effectors of miR-155 and miR-3173 activity in cancer." (PMID 40722677, 2025). "The modules also contained genes like LRRN4CL, NAV3 and STMN1 that have not yet been investigated in cancer research." (PMID 29371966, 2017).
tumor (19 papers, 2012 to 2025). "Subsequent functional experiments support NAV3, that harbours the most strongly associated risk variants, as a tumour suppressor gene in endometrial cells." (PMID 40633141, 2025). "Although neither Spred1 nor Nav3 mutations affected tumor cell sensitivity to EGFR inhibition with afatinib, loss of Spred1 or Nav3 increased sensitivity of EGFRvIII-tumor cells to MEK inhibitor treatment with trametinib." (PMID 32727536, 2020). "However, some genetic mutations, such as those in HLA-B, MEF2A, RHOA, and NAV3, were associated with a high tumor proliferation index in this study." (PMID 33747936, 2021). "Our demonstration that NAV3 aberrations are linked to inflammation and cell proliferation pathways, and finally to lymph node metastasis, may thus identify the cell population responsible for the spread of the initially local tumour." (PMID 22173670, 2012). "Downregulation of NAV3 in endometrial cell lines accelerated cell division and wound healing capacity whereas NAV3 overexpression reduced cell survival and increased cell death, indicating that NAV3 acts as a tumour suppressor in endometrial cells." (PMID 40633141, 2025). "Taken together, NAV3 downregulation accelerated tumour cell division and migration of endometrial cells, whereas its overexpression accelerated tumour cell death." (PMID 40633141, 2025). "The lowest expression of NAV3 is found in pseudopalisading cells, which are situated within the cellular tumor mass in proximity of necrotic areas." (PMID 39097525, 2025). "Conceivably, by regulating microtubule dynamics, NAV3 inhibits the random mode of cell migration and restrains dissemination of tumor cells." (PMID 25678558, 2015). "This response was associated with induction of a specific group of genes, including NAV3, a putative tumor suppressor whose mechanism of action is poorly understood." (PMID 25678558, 2015). "Although the downregulation of NAV3 in areas within the cellular tumor and its low level of expression in high‐grade GBM suggest that it acts as a tumor suppressor, survival data for newly diagnosed IDHwt GBM cases indicate that high NAV3 expression is associated with worse survival." (PMID 39097525, 2025). "To investigate whether spheroid‐cultured cells re‐express NAV3 upon migration from the sphere, reflecting cells disseminating from the tumor mass, we prepared U251 cells stably expressing the photoconvertible fluorophore Dendra2 (U251‐Dendra2)." (PMID 39097525, 2025). "A similar trend of differential NAV3 expression, with low levels observed in cells residing within the tumor sphere core and higher levels in cells at the tumor spheroid edges, respectively, was also detected in our samples from both established GBM cell lines and patient‐derived GSC cultures." (PMID 39097525, 2025). "We further provide functional evidence for NAV3 to be a tumour suppressor in endometrial cells." (PMID 40633141, 2025). "However, the exact pathway by which NAV3 aberrations aid metastasis and tumor progression in patients and in animal models remains to be elucidated." (PMID 32029709, 2020). "With the exception of clonal Pdgfra and Nav3 insertions in one tumor, transposon insertions in MAPK/PI3K pathway and neurodevelopmental genes (including Nf1, Pten, Pik3r1, Ptprj, Sox6, Sox5, and Tcf4) were subclonal in these tumors, implying these were late evolutionary events." (PMID 32727536, 2020). "How exactly NAV3 aberrations support metastasis and tumor progression in patients and in animal models remains unclear." (PMID 25678558, 2015). "In conclusion, NAV3 copy number changes may provide at least two growth advantages to a subpopulation of tumour cells." (PMID 22173670, 2012). "Tumour cells with NAV3 aberrations and abnormal localisation of beta-catenin would become less susceptible to growth control mechanisms by surrounding cells, whereas they also become more susceptible to growth promotion by tissue inflammatory signals, including IL23." (PMID 22173670, 2012).